NEGR1 (neuronal growth regulator 1)
Diseases named in the same sentence as NEGR1 in open-access papers (continued):
Sharing a sentence is not in itself a finding about the gene and the disease.
Obesity (continued). "Eighteen of those genes have reported associations with T2D and obesity in humans; of these genes there was most marked evidence for CLEC10A, MAPK8IP1, NEGR1, NQ01 and INHBE genes." (PMID 34391409, 2021). "For example, the NEGR1 gene, which is strongly expressed in the brain, has been reported to affect neuronal control of food intake and promote obesity." (PMID 33910581, 2021). "The comprehensive series of GWASs presented here validates associations of obesity and BMI found in previous studies, such as the FTO and NEGR1 loci." (PMID 31888951, 2020). "The strongest associations occurred between the NEGR1 and KLRB1 gene and obesity and morbid obesity and the NEGR1 gene and abnormal glucose." (PMID 31888951, 2020). "The genes reviewed here are FTO, NRXN3, NPC1, NEGR1, MTCH2, and GNPDA2, which were chosen for their association with obesity and their influence on NDgD or NDvD." (PMID 32982666, 2020). "The purpose of this study was to evaluate the association between CNVs in specific regions of LEPR, NEGR1, ARHGEF4, CPXCR1, and INS and in four intergenic regions (1p36.33b, 12q15c, 15q21.1a, and 22q11.21d) and obesity in Mexican children." (PMID 28428959, 2017). "The analysis of CNVs in six regions corresponded to five genes previously associated with obesity, LEPR (intron 2 and intron 3), NEGR1, ARHGEF4, CPXCR1, and INS, and four intergenic regions (1p36.33b, 12q15c, 15q21.1a, and 22q11.21d)." (PMID 28428959, 2017). "GWAS identified SNPs near the neuronal growth regulator 1 (NEGR1) gene associated with BMI variation and obesity." (PMID 25825681, 2015). "This allowed us to investigate the effects of altered hypothalamic Negr1 expression on the regulation of energy balance in satiated and starved rats, thereby providing insight into the role of Negr1 in the etiology of obesity." (PMID 25077509, 2014). "The association of six European obesity-related SNPs in or near FTO, NPC1, ENPP1, NEGR1, GNPDA2 and MC4R genes with risk of obesity was tested in 1,463 school-aged Mexican children (Ncases = 514; Ncontrols = 949)." (PMID 23375129, 2013). "We found strong associations with severe obesity for SNP rs9939609 within the FTO gene (P = 9.3×10−8) and SNP rs2815752 near the NEGR1 gene (P = 3.6×10−4), and directionally consistent nominal associations (P<0.05) for 12 other SNPs." (PMID 23950990, 2013). "In this context, our findings suggest that the NEGR1 rs2815752 SNP contributes to the genetic risk of severe adult obesity, likely driven by the alternative signal, but that the effects may be predominantly relevant at lower points on the continuum of severe adult obesity." (PMID 23950990, 2013). "Although the association between both MC4R and NEGR1 and risk of obesity has been confirmed in a plethora of studies and populations, the ENPP1 association signal with obesity is more controversial." (PMID 23375129, 2013). "A 45-kb deletion near NEGR1 gene and a 50-kb deletion upstream of GPRC5B gene previously associated to obesity and body mass index were also identified." (PMID 23844243, 2013). "Recently, analysis of GWAS-derived obesity gene variants provided evidence of positive natural selection at the FTO, NEGR1, SH2B1 and FAIM2 loci." (PMID 22043165, 2011). "Among the 15 obesity-associated SNPs that were assessed by family-based TDT analysis for association with PCOS, rs2815752 near NEGR1 was nominally significant (P = 0.013)." (PMID 21283731, 2011). "We identified RPL31P12, NEGR1, and DCC as common risk genes for obesity and depression." (PMID 40405979, 2025). "NEGR1 was one of the first genes identified in GWASs for BMI, including a meta-analysis of 15 publications with more than 30,000 participants, and demonstrated compelling evidence for a relation with obesity in adults and children." (PMID 38849516, 2024).
Obesity (continued). "Given that obesity is considered a chronic state of low-grade inflammation, it was not surprising to observe considerable increases in the expression of inflammatory cytokines, IL-1 and IL-6, in adipocytes and macrophages in Negr1−/− mice." (PMID 37187893, 2023). "Other biological mechanisms, such as neuroendocrine changes in the leptin-melanocortin pathway and overlapping genetic variation (e.g., OLFM4 and NEGR1), could also explain the correlation between obesity and depression." (PMID 37621933, 2023). "Therefore, the current study has been undertaken to compute the GRS based on five obesity-linked key loci including MC4R rs17782313, BDNF rs6265, FTO rs1421085, TMEM18 rs7561317, and NEGR1 rs2815752 in this at-risk and under-represented population." (PMID 33859285, 2021). "A very limited number of studies have examined the association of the NEGR1 rs2815752 with overweight/obesity in non-Caucasians, with no such study ever performed in Pakistani population." (PMID 32419576, 2020). "In addition, mice carrying a loss-of-function mutation (NEGR1-I87N) showed decreased food intake but normal energy expenditure, thereby supporting the positive correlation between NEGR1 expression and obesity." (PMID 32419576, 2020). "Recently, NEGR1 has been found to be involved in intracellular cholesterol homeostasis, which signifies its non-CNS function associated with human obesity." (PMID 32419576, 2020). "It has been proposed that NEGR1 could modulate the intracellular cholesterol trafficking, suggesting its implication in human obesity." (PMID 32982666, 2020). "However, in vivo studies have shown varying results for correlation between the expression level of NEGR1 and manifestation of obesity, perhaps owing to highly complex regulatory processes of energy homeostasis." (PMID 32419576, 2020). "The aim of this study was to investigate if the Negr1-Fgfr2 pathway was modulated by antidepressant treatment, since this gene has been genetically associated to both MDD and obesity, two co-occurring conditions believed to share common neurobiological alterations." (PMID 32751911, 2020). "Furthermore, we found nominal associations between obesity risk or BMI variation and the following SNPs: ENPP1 rs7754561, MC4R rs17782313 and NEGR1 rs2815752." (PMID 23375129, 2013). "Furthermore, we found nominal associations between risk of obesity or BMI and the following SNPs: ENPP1 rs7754561, MC4R rs17782313 and NEGR1 rs2815752." (PMID 23375129, 2013). "However, further studies with increased power are required to confirm our finding that, contrary to the early onset form, there is a relatively smaller contribution of the NEGR1 locus at the extreme tail of the severe adult obesity spectrum." (PMID 23950990, 2013). "Apart from those in FTO, several of the identified SNPs are located in or near genes clearly related to appetite regulation, and recently, five of the novel obesity loci (SH2B1, KCTD15, MTCH2, NEGR1 and BDNF) were indicated to be associated with dietary macronutrient intake levels." (PMID 23861046, 2013). "In both studies, we genotyped six SNPs that are known to be associated with risk of obesity in European populations: rs17782313 near MC4R; rs2815752 near NEGR1; rs7754561 near ENPP1; rs1805081 in exon 6 of NPC1; rs10938397 near GNPDA2 and rs1421085 in intron 1 of FTO." (PMID 23375129, 2013). "Our combined association studies in human and pig in the predefined fatness related pig QTL region revealed three most likely genes, FAM73A, NEGR1 and TTLL7, as being responsible for genetic predisposition to common forms of obesity, especially subcutaneous fat thickness." (PMID 21311593, 2011). "In addition, NEGR1 regulates body weight by influencing energy balance, lipogenesis, transport, and brain regions that control eating behavior, such as the hypothalamus and cerebellum, highlighting its potential role in the pathogenesis of obesity." (PMID 40405979, 2025).
Obesity (continued). "The aim of this study was to assess the effects of deletion of Negr1 on the monoaminergic circuitry as one of the mechanisms through which NEGR1 could be involved in the pathogenesis of depression and possibly in the pathogenesis of obesity." (PMID 36552158, 2022). "Taken together, these data suggest that Negr1 is involved in the maintenance of intra-parenchymal neurites, with a reduced production by obese adipocytes resulting in a lack of trophic support that contributes to the degeneration of sympathetic terminals in obesity." (PMID 36433953, 2022). "Thus, Negr1 is a key molecular factor in the disrupted adipose-sympathetic crosstalk in obesity." (PMID 36433953, 2022). "Interestingly, some genes associated with obesity were also associated with AD by different genetic approaches: candidate gene approach FTO, by differentially expressed genes NRXN3, NPC1, NEGR1, or by GWAS approach: LEPR, BDNF, TNFα, and MTCH2." (PMID 32982666, 2020). "However, a very limited number of studies have examined the association of the NEGR1 rs2815752 with overweight/obesity in non-Caucasians with no such study ever performed in Pakistani population." (PMID 32419576, 2020). "Notably, NEGR1 and MC4R are—found to be associated with obesity across multiple lines of evidence." (PMID 29795655, 2018). "Our study suggests that higher susceptibility to obesity estimated as a GRS of 13 obesity-associated SNPs associates with lower total energy intake but with higher fiber intake and that some of the obesity loci like the NEGR1 locus may regulate food intake." (PMID 23861046, 2013). "Recently the GIANT consortium reported that the NEGR1 obesity-associated SNPs they detected seemed to be in strong linkage disequilibrium with nearby copy number variations (CNV), although there is currently no functional evidence to support the involvement of the CNV in non-syndromic human obesity." (PMID 21311593, 2011). "Thus, we demonstrate that the currently known major common variants related to obesity overlap to a substantial degree between children and adults confirming previous observations for FTO, MC4R, TMEM18, NEGR1 and extending this observation to SEC16B, BDNF and BCDIN3D;." (PMID 20421936, 2010). "SMR analysis results identified NEGR1 and RPL31P12 as genetic links affecting the interaction between depression and obesity." (PMID 40405979, 2025). "Compared to the normal tissues, the expression level of each of the three obesity-related genes (LEPR, NEGR1, and POMC) in cancer tissues was found to be insignificant." (PMID 33299884, 2020). "Previous studies have identified variation in the copy number of the candidate regions near the neuronal growth regulator 1 (NEGR1) locus, chromosome 10q11.22, 11q11, and 10q26.3 with obesity." (PMID 31248128, 2019). "In this study, we found significant differences in the copy numbers among children with obesity compared to those in normal weight children for LEPR, NEGR1 ARHGEF4, CPXCR1, and INS and four intergenic regions previously associated with obese children." (PMID 28428959, 2017). "Our results indicate a possible contribution of CNVs in LEPR, NEGR1, ARHGEF4, and CPXCR1 and the intergenic regions 12q15c, 15q21.1a, and 22q11.21d to the development of obesity, particularly abdominal obesity in Mexican children." (PMID 28428959, 2017). "Because obesity contributes to systemic inflammation, and Negr1 knockout mice showed increased WAT adiposity, we examined the mRNA expression of several cytokines using epididymal WAT (eWAT) of Negr1−/− mice." (PMID 37187893, 2023). "Notably, reduced levels of adipose-sympathetic innervation and Negr1 abundance are also observed in DIO mice, although to a lesser extent than in ob/ob animals, as the DIO mouse is a milder model of obesity." (PMID 36433953, 2022). "This last GWAS identifies strong associations with extreme obesity, including established variants in the FTO and NEGR1 genes, as well as loci not yet linked to obesity." (PMID 31888951, 2020).
Obesity (continued). "Two obesity-related genes, such as LEP and NEGR1, may play a substantial role in the occurrence of two types of cancers (BRCA and BLCA)." (PMID 33299884, 2020). "Many of the obesity-related parameters investigated in our study have not been studied before in relation to the NEGR1 rs2815752." (PMID 32419576, 2020). "Association studies of CNVs with obesity often involving extreme obesity phenotypes with or without syndromic features have identified candidate regions near the NEGR1 locus and chromosome 10q11.22, as well as on chromosomes 11q11 and 10q26.3, among others." (PMID 28428959, 2017). "Among the new discovered loci, ATXN2L, NEGR1 and SH2B1 have also shown a relationship with obesity." (PMID 24267414, 2013). "SNPs in SH2B1, SFRS10 and KCTD15 associated with increased risk of overweight, but not with obesity, while the risk alleles in MC4R and NEGR1 associated with increased risk of obesity, but not with overweight." (PMID 23861046, 2013). "Leaving the hypothesis-free approach and focussing on known GWAS-based candidate markers, we were able to substantiate another four loci (NEGR1, SEC16B, BDNF and BCDIN3D) of the 16 obesity loci previously detected in GWAS." (PMID 20421936, 2010). "Hence, some obesity-related genes (LEPR, NEGR1, TMEM18, and SH2B1) may play critical roles in preventing progression and metastasis of kidney cancer." (PMID 33299884, 2020). "The comparison of changes in the expression levels of obesity-related genes between the occurrence of cancer and patients' survival revealed four obesity-related genes (LEPR, NEGR1, TMEM18, and SH2B1), which might play critical roles in preventing the progression and metastasis of kidney cancer." (PMID 33299884, 2020). "More recently, NEGR1 deficiency in mice has been found to induce abnormal fat deposition in various peripheral tissues, particularly fat and liver tissue cells, again indicating that the obesity-related function of NEGR1 is not restricted to the CNS but extends to peripheral tissues as well." (PMID 32419576, 2020). "Although the mechanism of most genetic loci predispose individuals to obesity is not clear so far, evidence indicated that they were involved in energy uptake (FTO, MC4R, PCSK1, and BDNF) and adipocyte differentiation (FTO, TMEM18, BDNF, MTCH2 and NEGR1)." (PMID 24626232, 2014). "To date, the in vivo function of NEGR1 is unknown and functional models that confirm the proposed role of NEGR1 in the development of obesity have not been reported." (PMID 22844493, 2012). "Additionally, other causal genes are highly expressed or known to act in human brain function (i.e., NEGR1, GNPDA2, CYP46A1, DGKH) and various carcinomas (i.e., PMAIP1, HORMAD1, FES, BCAS3), indicating the potential role of metabolic dysregulation in the pathogenesis of obesity and cardiac events." (PMID 33910581, 2021).
depression (45 papers, 2017 to 2026). "Negr1, a molecule regulating neuronal growth and connectivity, has been linked to depression-relevant behaviors in animal models." (PMID 41588420, 2026). "These morphological abnormalities in the neurons are likely associated with the observed anxiety- and depression-like behaviors in Negr1 KO mice." (PMID 40388597, 2025). "Genome-wide association studies (GWAS) have repeatedly identified NEGR1 as a gene of interest in major depressive disorder, schizophrenia, and body mass index across diverse populations." (PMID 41440084, 2025). "Neuronal growth regulator 1 (NEGR1) has been identified as a critical risk factor for major depressive disorders in humans." (PMID 40886916, 2025). "Recent meta-analyses using the Genome-Wide Association Study (GWAS) have identified a single-nucleotide polymorphism (SNP) of Negr1 gene associated with the diagnosis of major depression." (PMID 38370417, 2024). "NEGR1 has been reported to be associated with major depressive disorder in several GWAS and to be downregulated in the CA1 and dentate gyrus (DG) regions in major depressive disorder." (PMID 39558356, 2024). "Genome-wide association studies found substance use disorder and depression are frequent comorbidities, and significant correlation with NEGR1 expression in the hypothalamus and DRD2 in the NAc." (PMID 38164471, 2023). "The existence of an association between NEGR1 and Alzheimer’s disease has been investigated due to the frequent comorbidity with major depression." (PMID 37895235, 2023). "Accumulating evidence indicates that NEGR1 is a generic risk factor for various psychiatric diseases including autism and depression." (PMID 35406805, 2022). "Recently, multiple genome-wide analyses have shown that genetic alterations in NEGR1 are associated with many major neurological disorders such as dyslexia, schizophrenia, Alzheimer’s disease, and depression." (PMID 35406805, 2022). "In independently created Negr1−/− mice, it has been shown that Negr1 deficiency results in alterations in adult neurogenesis and hippocampal dentate gyrus (DG) synaptic transmission and leads to anxiety- and depression-like behaviors." (PMID 36552158, 2022). "In the major studies that have recently linked NEGR1 with depression, the diagnosis has been specified as MDD (major depressive disorder), broad depression, and unipolar depression." (PMID 36552158, 2022). "Studies have shown that NRXN1-α knockout mice exhibit social behavior disorders and increased autism-like symptoms such as aggressive behavior, whereas variations in the NEGR1 gene regulatory region are associated with major depressive disorder." (PMID 33391332, 2020). "Gene variants in a regulatory region upstream of the NEGR1 gene have been associated with major depressive disorder but also with low white matter integrity and intelligence." (PMID 29479305, 2018). "In our Australian sample of 3664 unrelated major depression cases and 7113 unrelated controls, SNP rs10514299 between TMEM161B and MEF2C and SNP rs11209948 near NEGR1 were nominally associated with major depression (P⩽0.05)." (PMID 28509901, 2017). "Taken together, alterations in species richness and abundance of gut microbiota in Negr1 KO mice are associated with NEGR1 deficiency, which may contribute to anxiety- and depression-like behaviors alongside neuronal structural abnormalities." (PMID 40388597, 2025). "in early life may be associated with neuronal structural defects and depression-like behaviors caused by NEGR1 deficiency." (PMID 40388597, 2025). "More recent studies using transgenic mouse models have highlighted the role of Negr1 in adult brain neurogenesis (hippocampus and olfactory) and its association with affective behaviors and neuropsychiatric disorders such as anxiety and depression." (PMID 41440084, 2025).